CAPN3 (calpain 3)
Description:
Calcium-regulated non-lysosomal thiol-protease. Proteolytically cleaves CTBP1 at 'His-409'.
Synonyms: nCL-1; CANP3; CANPL3; p94; LGMD2; LGMD2A; LGMDD4; LGMDR1
Tractability: Small molecule: a structure with a bound ligand is known. Antibody: its Gene Ontology location is reachable by antibodies, with medium confidence. PROTAC: ubiquitination databases record sites on it.
Gene: Protein-coding gene on chromosome 15 (42,359,498 to 42,412,949, forward strand). Ensembl gene ENSG00000092529.
Subcellular location: Cytoplasm; Nucleus, nucleolus
Pathways (Reactome):
Extracellular matrix organization: Degradation of the extracellular matrix
Gene Ontology:
Molecular function: catalytic activity; cysteine-type peptidase activity; peptidase activity; protein binding; titin binding; calcium ion binding; calcium-dependent cysteine-type endopeptidase activity; molecular adaptor activity; sodium ion binding; structural constituent of muscle
Biological process: calcium-dependent self proteolysis; negative regulation of apoptotic process; negative regulation of protein sumoylation; positive regulation of DNA-templated transcription; protein catabolic process; protein destabilization; proteolysis; regulation of canonical NF-kappaB signal transduction; self proteolysis; apoptotic process; cellular response to calcium ion; cellular response to salt stress; muscle cell cellular homeostasis; muscle organ development; muscle structure development; myofibril assembly; negative regulation of DNA-templated transcription; positive regulation of proteolysis; positive regulation of release of sequestered calcium ion into cytosol; positive regulation of satellite cell activation involved in skeletal muscle regeneration; protein localization to membrane; protein-containing complex assembly; response to calcium ion; response to muscle activity; sarcomere organization; and 3 more
Cellular component: cytoplasm; nucleolus; nucleus; cytosol; myofibril; plasma membrane; protein-containing complex; T-tubule; Z disc
Genetic constraint (gnomAD): Loss-of-function variants: 75 observed, 101.44 expected, observed/expected ratio (o/e) 0.74, 90% interval 0.61 to 0.9. The upper end of that interval is the gene's LOEUF score, 0.9, which puts it in group 3 of 6, group 1 being the genes least tolerant of losing a copy. Missense variants: 1,005 observed, 1,082.5 expected, observed/expected ratio (o/e) 0.93, 90% interval 0.88 to 0.98. Synonymous variants: 375 observed, 388.76 expected, observed/expected ratio (o/e) 0.96, 90% interval 0.89 to 1.05.
Gene-disease validity (ClinGen):
ClinGen rates the evidence that CAPN3 causes each of these diseases.
autosomal recessive limb-girdle muscular dystrophy (autosomal recessive): Definitive. Autosomal recessive form of limb-girdle muscular dystrophy.
muscular dystrophy, limb-girdle, autosomal dominant (autosomal dominant): Definitive.
Homologues: Orthologues: chimpanzee CAPN3 (99% identical), macaque CAPN3 (98% identical), rat Capn3 (94% identical), mouse Capn3 (93% identical), rabbit CAPN3 (93% identical), dog CAPN3 (93% identical), pig CAPN3 (92% identical), guinea pig CAPN3 (88% identical), tropical clawed frog capn3 (73% identical), zebrafish capn3a (59% identical), zebrafish capn3b (56% identical), Caenorhabditis elegans clp-1 (29% identical), and 7 more. Paralogues in human: CAPN9 (47% identical), CAPN1 (46% identical), CAPN11 (43% identical), CAPN2 (43% identical), CAPN8 (42% identical), CAPN12 (35% identical), CAPN14 (32% identical), CAPN5 (27% identical), CAPN13 (26% identical), CAPN6 (23% identical), CAPN10 (20% identical), CAPN7 (19% identical), and 8 more.
Diseases named in the same sentence as CAPN3 in open-access papers:
CAPN3 is named in the same sentence as 104 diseases in open-access papers, as found by Europe PMC text mining. Sharing a sentence is not in itself a finding about the gene and the disease. The quoted sentences say what the papers report.
calpainopathy (69 papers, 2007 to 2026). "The majority of these individuals had biallelic variants in the CAPN3 gene (30%), indicative of calpainopathy." (PMID 41695778, 2026). "LGMDR1 (previously referred to limb-girdle muscular dystrophy type 2A) is caused by a recessive mutation in the Calpain3 (CAPN3) gene." (PMID 39403691, 2025). "This represents the first description of the heterozygous p.Arg493Gln calpain 3 variant as a potential cause of mild calpainopathy." (PMID 39703226, 2024). "Patient with variants in the CAPN3:c.[700G > A];[1746-20C > G] clinically presented calpainopathy: proximal weakness and atrophy, muscle pain, walking difficulties and spine deformities." (PMID 38758368, 2024). "Despite the rarity of CAPN3 calpainopathy, but given the high prevalence of CAPN3:c.550del variant, the homodisomy of CAPN3 recessive alleles should be evaluated in patients with unexpected muscle abnormalities with PWS or AS." (PMID 39062725, 2024). "LGMD2A (Calpainopathy), caused by pathogenic variants in the CAPN3 gene, presents with variable severity, from mild to severe, with early involvement of the pelvic muscles followed by the shoulder muscles." (PMID 39596609, 2024). "Among known CAPN3 variants, the c.550del is the most prevalent variant in Croatia and has been frequently reported in patients with calpainopathy from countries across Europe." (PMID 39062725, 2024). "In this retrospective study, the cohort consisted of seven patients exhibiting the CAPN3 (NM_000070.3) mutation and a phenotype compatible with calpainopathy at a single center in Türkiye." (PMID 38812636, 2024). "In this retrospective study, we aimed to evaluate the clinical and molecular results of our patients with calpainopathy and to examine the CAPN3 variants in Turkish and global populations." (PMID 38812636, 2024). "This is the first description of the heterozygous p.Arg493Gln variant in CAPN3 as a potential cause of mild calpainopathy." (PMID 39703226, 2024). "The CAPN3:550del variant has been reported by several studies in patients in the eastern Mediterranean region with suspected calpainopathy." (PMID 39062725, 2024). "In the Turkish and global calpainopathy cohorts, missense mutations were the most common variants associated with calpainopathy in the CAPN3 gene." (PMID 38812636, 2024). "The isodisomy in the 15q15.1 region resulted in the isozygosity of the CAPN3:c.550del (p.Thr184fs) variant in the proband, which in turn led to the diagnosis of calpainopathy." (PMID 39062725, 2024). "CAPN3-associated calpainopathy is a rare limb–girdle muscular dystrophy with a prevalence of 1:100,000." (PMID 39062725, 2024). "To this end, we focused on calpainopathy disease, the most common limb-girdle muscular dystrophy, in which complex metabolic alterations have been reported as indirect defects of the CAPN3 gene mutation." (PMID 39759341, 2024). "This analysis revealed a pathogenic variant in the CAPN3 (HGNC:1480) gene that is associated with calpainopathy, a rare limb-girdle muscular dystrophy (MIM#253600)." (PMID 39062725, 2024). "Pathogenic variants of the CAPN3 gene cause calpainopathy (LGMD-R1), which is typically observed in patients aged 2–40 years." (PMID 39678382, 2024). "The CAPN3:c.550del (p.Thr184fs) variant is a pathogenic frameshift variant (ClinVar ID: 17621) and has been reported in autosomal recessive calpainopathy patients." (PMID 39062725, 2024). "CAPN3 has been reported to have multiple muscle cell functions and mutations in this protease cause limb-girdle muscular dystrophy type 2A." (PMID 37051601, 2023). "Loss-of-function mutations of CAPN3 inactivate its proteolytic function, playing an important role in the pathogenesis of calpainopathy, but the precise mechanism of calpainopathy has remained elusive." (PMID 37974208, 2023). "Calpainopathy is caused by a defect in the calpain-3 gene (CAPN3) located in the chromosomal region 15q15.1-q21.1." (PMID 37974208, 2023).
calpainopathy (continued). "Both probands were originally diagnosed with calpainopathy, each of them carrying two known pathogenic CAPN3 mutations in the coding sequence." (PMID 34720847, 2021). "Reduction of calpain-3 protein amount in most Western blot samples further supports the pathogenicity of the identified variants, as it is highly specific for a primary calpainopathy." (PMID 34720847, 2021). "Since mdm muscles exhibit CAPN3 deficiency, the mdm phenotype was initially thought to be linked to limb girdle muscular dystrophy type 2A, which is also characterized by CAPN3 deficiency often associated with CAPN3 null mutations." (PMID 32492876, 2020). "Calpainopathies are muscular dystrophies that result from genetic mutations in CAPN3, revealing its critical function in healthy muscle." (PMID 32492876, 2020). "Limb-girdle muscular dystrophy 2A (LGMD2A) was the first-described calpainopathy, which is caused by mutations in the gene encoding muscular calpain-3 (CAPN3)." (PMID 30895192, 2019). "LGMDR1, also known as calpainopathy and previously symbolized LGMD2A, is caused by homozygous or compound heterozygous mutation in the CAPN3 gene encoding for the proteolytic enzyme calpain 3 (CAPN3)." (PMID 31540302, 2019). "Of interest, loss-of-function mutations in calpain-3 are known to cause limb girdle muscular dystrophy type 2a (LGMD2a; also called calpainopathy), and transgenic reduction of calpain-3 in mice causes severe Ca2+ dysregulation." (PMID 28330496, 2017). "CAPN3 dysfunction causes the limb-girdle muscular dystrophy (LGMD) 2A also called calpainopathy, which is the most common type of LGMD, with 30 % of the patients." (PMID 26503425, 2016). "For example, mutations that disturb localized protein interactions with calpain-3 cause limb-girdle muscular dystrophy type 2A." (PMID 23055945, 2012). "Limb-girdle muscular dystrophy type 2A (LGMD2A) is a recessive genetic disorder caused by mutations in calpain 3 (CAPN3)." (PMID 19015733, 2008). "One such gene is CAPN3, known to cause calpainopathy, an autosomal recessive muscular dystrophy." (PMID 39062725, 2024). "In addition, the study analyzed the variants of Turkish and worldwide patients with calpainopathy and revealed the characteristics of the CAPN3 gene comparatively." (PMID 38812636, 2024). "CAPN3-caused calpainopathy and DMD have overlapping clinical features, therefore, this could have been the cause of the disease as well." (PMID 36361862, 2022). "Although the underlying pathological mechanisms involved in LGMDR1 are not well known, studies of Capn3 knockdown mice identified a human calpainopathy-like phenotype, thus indicating that this disease is caused by defects in the CAPN3 gene (MIM #114240), which is located on chromosome 15q15." (PMID 34863162, 2021). "The term calpainopathy was coined to identify the cluster of signs and symptoms that define the phenotype that originated as consequence of pathogenic mutations that are harbored in the CAPN3 gene." (PMID 31991774, 2020). "In this manuscript, the case of a patient affected by LGMD2A is reported, for which the application of a defined custom designed NGS panel allowed to confirm the diagnosis of calpainopathy linked with two heterozygous variants in CAPN3, namely c.550delA and c.1813G>C." (PMID 31263448, 2019). "In this study, we observed increased passive tension (PT) of skinned myofibers from patients with myofibrillar myopathy (MFM) caused by FLNC mutations (MFM-filaminopathy) and limb-girdle muscular dystrophy type-2A due to CAPN3 mutations (LGMD2A), compared to healthy control myofibers." (PMID 28915917, 2017). "For example, loss of function of the full-length isoform of calpain 3 results in limb girdle muscular dystrophy type 2A, knocking out alleles of mouse CAPN 8 and CAPN 9 results in ethanol-induced gastric injury, and aberrant calpain 10 activation results in type 2 diabetes." (PMID 23855590, 2013).
calpainopathy (continued). "Indeed, a dominant form of calpainopathy may constitute a possible diagnosis in the relatively high proportion (~20%) of LGMD cases where only a single variant in CAPN3 is identified." (PMID 41373542, 2025). "CAPN3 was ranked high based on the strong clinical match with the disease autosomal recessive limb-girdle muscular dystrophy-1 (LGMDR1; blue shading)." (PMID 41491999, 2026). "Consistently with previous studies, our data confirm the predominance of CAPN3-related calpainopathy, accounting for half of our cases." (PMID 40870035, 2025). "This study shows that dysferlinopathy and calpainopathy are frequently occurring LGMD-R subtypes in the enrolled population (DYSF-associated LGMD-R2: 69/261 [26.44%] and CAPN3-associated LGMD-R1:61/261 [23.37%])." (PMID 39678382, 2024). "As proof of principle, we recapitulated disease-associated pathology of Duchenne muscular dystrophy and limb-girdle muscular dystrophy type 2A caused by loss of function of DMD and CAPN3, respectively." (PMID 38389096, 2024). "In the present study, we investigated calpain-3 protein expression in muscle dystrophy cases suspected to have calpainopathy, for which muscle enzyme histochemistry and immunohistochemistry were performed." (PMID 38561828, 2024). "Limb-girdle muscular dystrophy type 2A (LGMD R1 Calpain 3-Related, LGMD2A/R1), a prevalent form in many countries, is mainly caused by the calcium-activated neutral proteinase 3 (CAPN3) gene mutations." (PMID 39188286, 2024). "As a proof of principle, we induced genetic deficiencies for DMD (Duchenne muscular dystrophy, OMIM#310200) and CAPN3 (limb-girdle muscular dystrophy type 2A (LGMD2A), OMIM#253600) in healthy hiPSC-based 3D-TESMs." (PMID 38389096, 2024). "Limb-girdle muscular dystrophy type 2A results from alterations in the calpain-3 (CAPN3) gene, which results in a CAPN3 protein shortage." (PMID 38298311, 2024). "Calpain-3 (CAPN3) is specifically expressed in skeletal muscle, and its dysfunction is linked to limb-girdle muscular dystrophy type 2A." (PMID 34572540, 2021). "Calpainopathy (CAPN3, LGMDR1) represents the most frequent LGMD-subtype worldwide but was the second most common myopathy found in our cohort." (PMID 33250842, 2020). "It proves to be crucial for muscle cell homeostasis, as demonstrated in Limb-Girdle Muscular Dystrophy type 2A (LGMD2A, or calpainopathy), which is characterized by different CAPN3 point mutations and by muscle hypotrophy, hypoplasia and myonuclear apoptosis." (PMID 25658320, 2015). "Primary calpainopathy (LGMD2A, OMIM 253600), caused by mutations in the 40-kb CAPN3 gene (OMIM 114240, mapped to 15q15.1-q21.1), is the most frequent form of recessive LGMD, with a prevalence of 1∶15,000–1∶150,000 depending on the population." (PMID 25079074, 2014). "Genetic association studies have implicated calpains in disease pathologies including limb-girdle muscular dystrophy type 2A (LGMD2A, CAPN3), susceptibility to type II diabetes (CAPN10) and gastric cancer (CAPN8/9)." (PMID 22479198, 2012). "Calpain 3 (Capn3), also named p94, is a skeletal muscle tissue-specific protein known to be responsible for limb-girdle muscular dystrophy type 2A (LGMD2A)." (PMID 20421977, 2010). "While calpainopathies are classically inherited in an autosomal recessive manner, a small number of cases with autosomal dominant inheritance (LGMDD4) have also been reported and linked to specific CAPN3 mutations." (PMID 41373542, 2025). "Finally, it must be emphasized that this is a case study with limited genetic data but reporting an interesting observation on CAPN3 expression that will contribute to a better understanding of dominant calpainopathy." (PMID 40226307, 2025). "Diagnosis of calpainopathy depends mainly on the detection of calpain-3 protein expression." (PMID 38561828, 2024). "Furthermore, we aimed to investigate variations in the molecular profile of CAPN3 in individuals with calpainopathy from Türkiye and around the world." (PMID 38812636, 2024).
calpainopathy (continued). "However, contrasting studies report that normal CAPN3 protein levels are found in patients diagnosed with calpainopathy at the genetic level." (PMID 38812636, 2024). "Nonsense or loss-of-function mutations in the non-lysosomal cysteine protease calpain-3 result in limb-girdle muscular dystrophy type 2A (LGMD2A)." (PMID 33308300, 2020). "The importance of calpain-3 in skeletal muscle homeostasis is underlined by the fact that lack of calpain-3 leads to limb-girdle muscular dystrophy type 2A with sufferers becoming wheelchair-bound from early adulthood onwards." (PMID 29368185, 2018). "For example, skeletal muscle-specific calpain 3/p94 is a product of the gene responsible for limb-girdle muscular dystrophy type 2A (LGMD2A), demonstrating that the inactivation of tissue-specific calpains is a potential direct strategy for understanding some of the calpain functions." (PMID 20686710, 2010). "BACKGROUND: Calpainopathies, including limb-girdle muscular dystrophy recessive type 1 (LGMD R1) and the rare dominant type 4 (LGMD D4), are genetic neuromuscular disorders caused by pathogenic variants in the CAPN3 gene, which encodes calpain-3, a muscle-specific cysteine protease." (PMID 41761360, 2026). "The global prevalence of LGMDs is estimated to range from 0.8 to 6.9 per 100,000 individuals, with CAPN3-related calpainopathy (LGMD2A/R1) emerging as the most common subtype, followed by DYSF-related LGMD (LGMDR2)." (PMID 40870035, 2025). "Unlike other dystrophies, calpainopathy is caused by mutations in the CAPN3 gene, which codes for a calcium-dependent protease, calpain-3, involved in calcium homeostasis, and in the remodelling of sarcomeres, the multiprotein structures responsible for contraction." (PMID 39759341, 2024). "Sometimes calpainopathy patients may show normal protein expression with variation in CAPN3 gene." (PMID 38561828, 2024). "In this work, we presented a family with a positive history for LGMD2A (OMIM #253600, also known as calpainopathy) characterized by compound heterozygosity for two CAPN3 mutations." (PMID 32397577, 2020). "With the motif new substrates can be efficiently predicted, as shown by the increase in TPM and BOC levels in Calpainopathy patients and the regulation of PIAS proteins by CAPN3." (PMID 20694146, 2010). "In approximately 80% of cases with calpainopathy, the CAPN3 protein is observed as reduced or absent in immunoblot or immunohistochemical (IHC) tests." (PMID 38812636, 2024). "Limb-girdle muscular dystrophy type 2A (LGMD2A), a subtype with higher prevalence among LGMDs, does not arise from a defect of the structural cellular composition, but rather from a defect of a skeletal muscle-specific protease, the Calpain 3 (CAPN3)." (PMID 38020204, 2023). "Although the pathophysiology of calpainopathy has not been fully elucidated yet, some experimental and bioinformatic results show that CAPN3 targets the E3 ubiquitin proteins MuRF1 and TRIM32 as substrates." (PMID 35366260, 2021). "In contrast to one-time damage, the muscles from calpainopathy patients with defective or absent CAPN3 activity, particularly in the early stages of the dystrophic process, show an ongoing cycle of necrosis and regeneration." (PMID 29241457, 2017). "A previous demonstration of the complete absence of calpain-3 by IHC using fresh muscle tissue processed with the snap frozen technique was found to be 100% specific for calpainopathy." (PMID 28219397, 2017). "Therefore, we considered the band reduced or absent for calpain-3 protein, corresponding to the size of 94 kDa for the diagnosis of calpainopathy." (PMID 38561828, 2024). "Limb-girdle muscular dystrophy, LGMD, type 2A (calpainopathy) is one of the most common forms of LGMD worldwide and is caused by mutations in the CAPN3 gene, which encodes a skeletal muscle-specific Ca2+-activated nonlysosomal cysteine protease, CAPN3 (CAPN3)." (PMID 29241457, 2017).